RN7SL275P (RNA, 7SL, cytoplasmic 275, pseudogene)
Gene: Miscellaneous RNA gene on chromosome 4 (110,117,736 to 110,118,070, forward strand). Ensembl gene ENSG00000263940.
Homologues: Orthologues: macaque Metazoa_SRP (73% identical), macaque Metazoa_SRP (67% identical). Paralogues in human: Metazoa_SRP (63% identical), Metazoa_SRP (61% identical), RN7SL488P (61% identical), RN7SL744P (61% identical), RN7SL376P (61% identical), RN7SL619P (60% identical), RN7SL339P (60% identical), RN7SL48P (60% identical), RN7SL560P (60% identical), RN7SL440P (58% identical), RN7SL784P (58% identical), RN7SL134P (57% identical), and 702 more.